ANXA2 (annexin A2)
Diseases named in the same sentence as ANXA2 in open-access papers (continued):
Sharing a sentence is not in itself a finding about the gene and the disease.
breast carcinoma (continued). "Once more, analysis of this large breast cancer cohort appears to link ANXA2 expression with ER negative breast cancer, encompassing both the aggressive triple negative and HER-2 overexpressing subtypes." (PMID 32629869, 2020). "The expression of exo-AnxA2 was significantly higher in sera of breast cancer patients compared to non-cancer females (P < 0.0001)." (PMID 31992335, 2020). "Immunohistochemical analyses of human breast cancer tissues revealed AnxA2 and elevated tPA on the surface of cancer cells, but not normal cells, as well as evidence of inflammation within the tumor." (PMID 32575495, 2020). "Serum samples collected from breast cancer patients (n = 169) and non-cancer females (n = 68) were analyzed in a double-blind study for exo-AnxA2 protein levels." (PMID 31992335, 2020). "Therefore, we measured the expression of exo-AnxA2 levels in serum samples of ER+, HER2+, and TNBC breast cancer patients." (PMID 31992335, 2020). "The elevated expression of ANXA2 can contribute to the tumor progression in estrogen receptor (ER) negative breast cancer cell lines; pancreatic tumor progression can be inhibited by blocking VCAM1." (PMID 33287876, 2020). "Further, by categorizing the GSE42568 cohort according to ER expression, we see that ANXA2 expression is significantly upregulated in those with ER negative breast cancer tissue (p = 0.0094, Student’s t-test), which is consistent with our cell line data." (PMID 32629869, 2020). "In these latter studies, expression of AnxA2 has not yet been shown to correlate with activation of plasmin, as it has in breast cancer and glioblastoma." (PMID 32575495, 2020). "ANXA2 has been reported as an independent predictor of poor prognosis in breast cancer patients receiving neoadjuvant therapy, however overexpression of ANXA2 alone did not have a statistically significant impact on DRFS among GSE25066 patients." (PMID 31146747, 2019). "ATRA treatment in MCF-7 breast cancer cells reduce S100A10 but not annexin A2 transcript and protein levels, indicating that ATRA can regulate S100A10 levels independently of PML/RARα and annexin A2." (PMID 30572596, 2018). "Furthermore, AnxA1 prognostic impact relies on high AnxA2 expression and both are preferential for TNBC when compared to other breast cancer subtypes." (PMID 29416802, 2018). "Indeed, ANXA2 has been proved to sustain EMT and invasion of pancreatic ductal adenocarcinoma, induce hepatocellular carcinoma and breast cancer metastasis and was found up-regulated in highly invasive carcinomas." (PMID 27429043, 2016). "Anxa2 expression was also positively correlated with the expression of epidermal growth factor receptor (EGFR) and epithelial–mesenchymal transition (EMT) markers in breast cancer tissues and cell lines." (PMID 26307676, 2015). "Moreover, knockdown of Anxa2 impaired EGF-induced EMT, as well as the migration and invasion of breast cancer cells in vitro." (PMID 26307676, 2015). "Thus, our findings suggest a possible functional correlation between Anxa2 and EGFR during breast cancer aggravation." (PMID 26307676, 2015). "Moreover, we provided in vitro evidence that Anxa2 is required for EGF-induced EMT, as well as in the migration and invasion of breast cancer cells." (PMID 26307676, 2015). "In addition, Zhang has shown that the knockdown of ANXA2 in MDA-MB-435s cells downregulates the levels of plasmin, S100A10, and c-Myc and inhibits breast cancer proliferation and invasion." (PMID 24591759, 2014). "Overall, ANXA2 is overexpressed in acute lymphoblastic leukemia (ALL), APL, breast cancer, colorectal carcinoma (CRC), gastric cancer, glioma, hepatocellular carcinoma (HCC), lung cancer, multiple myeloma (MM), oral squamous cell carcinoma (OSCC), and pancreatic cancer." (PMID 24591759, 2014). "Absence of Annexin A1 expression coupled with presence of Annexin A2 expression is reported to correlate with a poor pathological response to induction chemotherapy in breast cancer." (PMID 23786757, 2013).
breast carcinoma (continued). "Further clinical should validate the potential use of AnxA2 as a diagnostic and/or prognostic tool in Her-2 negative, Herceptin-resistant and TNBC subsets of breast cancer." (PMID 22957061, 2012). "The immunohistochemical analysis of breast cancer clinical samples and of different clinical grades confirms a negative correlation of AnxA2 with Her-2 expression." (PMID 22957061, 2012). "This study reports a significant finding about the potential of AnxA2 as a diagnostic and/or prognostic marker as well as a therapeutic target in Her-2 negative, Herceptin-resistant and TNBC subset of breast cancer." (PMID 22957061, 2012). "This is the first report implying the reciprocal regulation of Her-2 and AnxA2 and the role of AnxA2 in Her-2 negative breast cancer and EGFR signaling." (PMID 22957061, 2012). "Within the breast cancer microenvironment, exosomes containing ANXA2 stimulate the activation of MAPK and NF-κB signaling pathways in macrophages, thereby mediating the secretion of the chemokines IL-6 and TNF-α to remodel the microenvironment to support breast cancer cell survival." (PMID 39972459, 2025). "Thus, we suggest the targeting of Annexin A2 to prevent its translocation or protein interactions may be an approach to halting the ECM and TME mediated progression of breast cancer." (PMID 37941562, 2023). "Moreover, other studies identified higher expression levels of serum exosomal-annexin A2 (exo-AnxA2) in female with breast cancer against noncancer, especially for TNBC rather than luminal and HER2-positive BC." (PMID 34659224, 2021). "Moreover, Anxa2 could activate STATS by directly bingding to STAT3, and consequently involve in the invasion and metastasis in breast cancer cells." (PMID 33903672, 2021). "However, we did not observe a difference between plasma annexin A2 from patients with early-stage breast cancer compared to healthy controls." (PMID 33406648, 2021). "Given the fact that breast cancer cells and tumors secrete significant amounts of exosomes, we hypothesize that exo-AnxA2 from AA TNBC patients will have higher amounts of exo-AnxA2 secreted in their serum which contributes to the aggressiveness of their disease." (PMID 31992335, 2020). "The immunoblotting data clearly suggest that the expression of AnxA2 is high in TNBC cell lines (HCC1937, HCC70, and HCC1395 cells) compared to ER+ (ZR75-1 cells), ER+/PR+ (MCF7, T47D, and HCC1428 cells), HER2+ (SK-BR-3 cells), and ER+/PR+/HER2+ (BT474 cells) breast cancer cell lines." (PMID 33374917, 2020). "As evident from Matrigel plug images, incubation of the plugs with breast cancer serum exosomes resulted in approximately 5.8-fold decrease in hemoglobin concentration with LCKLSL AnxA2 inhibitory peptide treatment, which did not occur with LGKLSL control peptide treatment." (PMID 31992335, 2020). "Furthermore, we did not observe any significant difference in AnxA2 levels between healthy and grade I breast cancer patients." (PMID 33374917, 2020). "In the present study, we observed that the prognostic value of serum AnxA2 in comparison to normal healthy females is very high in TNBC (AUC = 0.951, p < 0.0001) compared to ER+ (AUC = 0.427, p = 0.1830) and HER2+ (AUC = 0.783, p < 0.0001) breast cancer patients." (PMID 33374917, 2020). "Having shown that AnxA2 is present in the serum samples of breast cancer patients and predominantly localized at the surface of the exosomes, we measured the circulating concentrations of exo-AnxA2 in serum samples of breast cancer patients and non-cancer females." (PMID 31992335, 2020). "Furthermore they also reported that ATRA treatment reduced S100A10 expression but not ANXA2 mRNA or protein levels in the MCF-7 breast cancer cells." (PMID 30621740, 2019). "Finally, anti-ANXA2 mAbs significantly inhibited EGF-induced proliferation and metastasis by successfully blocking of EGFR homo-dimerization, phosphorylation and internalization in breast cancer." (PMID 29568351, 2018).
breast carcinoma (continued). "Interestingly, in both EGFR and Anxa2 high expression groups, E-cadherin presented a significantly higher rate of low expression (P = 0.0002), which indicates a combined effect of EGFR and Anxa2 on breast cancer EMT." (PMID 26307676, 2015). "Interestingly, recent studies provided evidences that Anxa2 is involved in EGFR signaling, and blocking AnxA2 function or knockdown of Anxa2 expression inhibits the activation of the EGFR downstream pathway and reduces cell migration in breast cancer cell line MDA-MB-231." (PMID 26307676, 2015). "However, the clinical significance of AnxA2 expression in breast cancer has not been reported." (PMID 33374917, 2020). "However, the expression of AnxA2 in breast cancer patients has not been reported." (PMID 33374917, 2020). "Ultimately, this knowledge suggests that targeting Annexin A2 merits investigation as a novel therapeutic strategy in treating the pharmacologically challenging ER negative subtype, and this may help prevent breast cancer progression to the later metastatic stages of disease." (PMID 32629869, 2020). "The level of serum exosomal AnxA2 was significantly higher in TNBCs than in ER + and HER2 + breast cancer subtypes as well as in females without breast cancer." (PMID 36096820, 2022). "Recent studies also demonstrated that female breast cancer patients have a higher expression level of serum exosomal-annexin A2 (Exo-AnxA2) than healthy subjects, especially for TNBC, rather than luminal and HER2-positive breast cancer." (PMID 36438660, 2022). "We also included the non-neoplastic astrocyte cell line, SC-1800, and the breast cancer cell line, MDA-MB-231 that we had previously shown to express very high levels of ANXA2." (PMID 32867190, 2020). "As shown hereafter, both ANXA2 and ANXA8 are not confined to acute promyelocytic leukemia and breast cancer, but are also involved in other cancers." (PMID 32823855, 2020). "Based on molecular subtypes, AnxA2 expression was significantly elevated in tumor tissues and serum samples of triple-negative breast cancer (TNBC) patients compared with other breast cancer subtypes." (PMID 33374917, 2020). "Our results suggest that the secretion of AnxA2 is high in TNBC cell lines compared to non-tumorigenic, ER+, PR+, and/or HER2+ breast cancer cell lines." (PMID 33374917, 2020). "Our results show that AnxA2 is also present in exosomes isolated from serum samples of non-cancer females and ER+, HER2+, and TNBC breast cancer patients." (PMID 31992335, 2020). "In addition, EpCAM- and AnxA2-positive exosomes are negative for the expression of calnexin and GM130, respectively, and show the purity of exosomes isolated from breast cancer serum samples." (PMID 31992335, 2020). "Moreover, we have previously shown that AnxA2 gene is overexpressed in tumor tissues of triple-negative breast cancer compared to ER+, PR+, and HER2+ breast cancer patients." (PMID 33374917, 2020). "From these observations, we conclude that AnxA2 is involved in EGFR downstream signaling, either directly or indirectly, in a Src dependent manner and significantly contributes to the survival, growth and progression of Her-2 negative breast cancer." (PMID 22957061, 2012).
hepatocellular carcinoma (76 papers, 2009 to 2025). A malignant tumor that arises from hepatocytes. "S100A10 regulates apoptosis and viability of hepatocellular carcinoma cells probably associated with ANXA2/Akt/mTOR pathway." (PMID 37420211, 2023). "As a tumor-associated protein, Annexin A2 promotes cancer progression including proliferation, invasion and metastasis in nasopharyngeal carcinoma, ovarian cancer, gliomas, hepatomas, pancreatic cancer and so on." (PMID 30341243, 2018). "The highest levels of ANXA2 expression were confirmed in MHCC97-H cells with high metastatic potential and ANXA2 expression is associated with high metastatic potential and invasion ability of hepatoma cells." (PMID 24348815, 2014). "For example, ANXA2 up-regulation was reported to be associated with human hepatocellular carcinoma, pancreatic adenocarcinoma, high-grade glioma, gastric carcinoma, acute promyelocytic leukemia and primary colorectal cancer." (PMID 21595958, 2011). "ANXA2, a member of the calcium-dependent membrane-bound protein family, has been implicated in the development of oncogenesis and various inflammatory diseases, such as hepatocellular carcinoma (HCC), systemic lupus erythematosus (SLE), and inflammatory bowel disease (IBD)." (PMID 37828081, 2023). "The immunoassay demonstrated high accuracy for the detection of ANXA2 in serum samples from hepatocellular carcinoma patients, with a wide range of ANXA2 concentrations (100 fg/mL-100 ng/mL) covered." (PMID 40038692, 2025). "In terms of therapeutic potential, it has been shown that silencing ANXA2 using shRNA effectively reduces hepatoma cell invasion, migration, and tumorigenicity." (PMID 40717977, 2025). "Annexin A2 also promotes immune escape of hepatocellular carcinoma, by upregulation of immune checkpoint molecules, and decreased expression of effector factors, including perforin, granzyme B (GZMB), interferon-γ, and TNF-α." (PMID 38519766, 2024). "In hepatocellular carcinoma, ANXA2 has been reported to promotes immune escape, by upregulation of immune checkpoint molecules, and decreased expression of effector factors." (PMID 38519766, 2024). "ANXA2 is overexpressed in several types of cancer, such as hepatocellular carcinoma (HCC), breast cancer, and NSCLC, and contributes to cancer development and progression." (PMID 38688909, 2024). "Blocking this interaction reduces the phosphorylation of EGFR and Annexin A2, suppressing mycoplasma-induced invasion and migration of gastric cancer cells, and improving the sensitivity of hepatocellular carcinoma cells to chemotherapy drugs." (PMID 37482693, 2023). "ANXA2 stimulates cell invasion in breast, brain, liver, and pancreatic cancers, and improves cell motility and adhesion in prostate and hepatocellular carcinoma cells." (PMID 37185759, 2023). "In summary, we basically concluded that S100A10 was involved in the growth process of hepatocellular carcinoma through the ANXA2/Akt/mTOR signaling pathway." (PMID 37420211, 2023). "TAGLN2-annexin A2 (ANXA2) interaction and NF-kappa B signaling pathway are related to the invasion and metastasis of hepatocellular carcinoma." (PMID 37363722, 2023). "A large number of studies have shown that ANXA2 is involved in the development of hepatocellular carcinoma and plays an important role in its growth, and high expression of ANXA2 is negatively correlated with the prognosis of hepatocellular carcinoma." (PMID 37420211, 2023). "For example, LINC01133 exerts tumor suppressor effects in hepatocellular carcinoma not only through the competing endogenous RNAs (ceRNA) mechanism that involves binding to miR-199a-5p, but also by binding to the ANXA2 protein." (PMID 35747817, 2022). "ANXA2 acted an as an oncogene in hepatocellular carcinoma progression, which was modified by SIRT6/UBE3A." (PMID 35977942, 2022).
hepatocellular carcinoma (continued). "LncRNA-MUF, also known as mesenchymal stem cell upregulated factor (lncRNA-MUF), promotes hepatocellular carcinoma by binding to ANXA2 to activate WNT/β-catenin signaling-mediated EMT." (PMID 35223453, 2021). "Zhang and co-workers demonstrated that knockdown of ANXA2 in hepatoma cell lines reduced cell migration and invasion." (PMID 34575275, 2021). "Consistent with previous studies, ANXA2 has been found to be highly expressed in hepatocellular carcinoma (HCC) tissues compared to adjacent normal tissues, furthermore, its high expression is in association with an aggressive phenotype in HCC." (PMID 34109194, 2021). "ANXA2 has been regarded as a biomarker in bladder cancer, clear cell renal cell carcinoma, hepatocellular carcinoma, and prostate cancer." (PMID 34026819, 2021). "In a large cohort study, serum annexin A2 was significantly elevated in early-stage hepatocellular carcinoma patients compared to healthy controls and patients with other malignancies such as lung or bowel cancer." (PMID 33406648, 2021). "It has been well-established that Anxa2 binds to p50 to promote NF-κB activation and cell survival in hepatocellular carcinoma and pancreatic cancer cell lines." (PMID 32244350, 2020). "Upregulation of ANXA2 was observed in many different cancer types, including hepatoma, pancreatic cancer, breast cancer, glioma, colorectal cancer, and GC." (PMID 31186633, 2019). "With the upregulation of ANXA2, the potential ability of metastatic and invasive is increased in hepatoma cell, shRNA-mediated ANXA2 silencing significantly inhibits cell invasion, migration, and tumorigenic potential." (PMID 31186633, 2019). "Abnormal expression of annexin A2 was found in hepatocellular carcinoma and other types of tumors, such as pancreatic cancer, gastric adenocarcinoma, prostate carcinoma, high-grade glioma, oral squamous cell carcinoma, and breast cancer." (PMID 30881525, 2019). "Annexin A2 mRNA level was significantly elevated in hepatocellular carcinoma (P < 0.001) and the ROC curve generated based on the mRNA level of Annexin A2 indicated that Annexin A2 can be a biomarker of high accuracy (AUC > 0.9) in hepatocellular carcinoma." (PMID 28963461, 2017). "ANXA2 expression was significantly higher (P<0.05) in hepatoma cells with a 5–8 fold increased expression compared with that of the LO2 cells." (PMID 24348815, 2014). "Annexin A2 was reported to regulate glioma cell invasion, tumor progression, migration and invasion of human hepatocellular carcinoma cells as well as intestinal epithelial cell migration." (PMID 25244316, 2014). "Down-regulation of annexin A2 in hepatocellular carcinoma cells reduced the secretion of MMP, migration ability, and invasive potential and also affected the cytoskeleton rearrangement of tumor cells." (PMID 24884814, 2014). "Among six proteins identified, Annexin A2, a regulatory protein, was reported to promote migration and invasion of hepatocellular carcinoma cells co-cultured with fibroblasts in vitro, but its function in fibroblasts is unclear." (PMID 25244316, 2014). "Silencing of annexin A2 expression significantly reduced cell adhesion of hepatocellular carcinoma cells and cell adhesion of myeloid cells to human and murine osteoblasts cells." (PMID 23945256, 2013). "It has been reported that Annexin A2 (ANXA2) is up-regulated in hepatocellular carcinoma (HCC), but the roles of ANXA2 in the migration and invasion of HCC cells have not been determined." (PMID 23950866, 2013). "The expression of annexin A2 in hepatocellular carcinoma is up-regulated at the transcriptional and translational level." (PMID 23519104, 2013). "Additionally, ANXA5 and ANXA2 expressions were upregulated in advanced hepatocellular carcinoma stages which were proposed as potentially useful biomarkers for poor survival in liver cancer patients." (PMID 40607003, 2025).